EPOR (erythropoietin receptor)
Diseases named in the same sentence as EPOR in open-access papers (continued):
Sharing a sentence is not in itself a finding about the gene and the disease.
glioma (7 papers, 2012 to 2024). A benign or malignant brain and spinal cord tumor that arises from glial cells (astrocytes, oligodendrocytes, ependymal cells). "The association of EPOR inhibition with TMZ treatment induces a greater decrease in glioma cell number as evidenced by the SER values of 1.78 and 2.44 for U87-shEPOR and U251-shEPOR cells respectively." (PMID 25544764, 2015). "We previously showed that the inhibition of EPOR expression on U87 glioma cells leads to a decrease in their doubling time and slows down the proliferation of U87 glioma cells in vitro as well as tumour growth in vivo." (PMID 25544764, 2015). "When radiotherapy is combined with EPOR inhibition, glioma cells exhibit a similar cell proportion in the G2/M phase before and 14h after radiation (about 50% of cells)." (PMID 25544764, 2015). "EPOR inhibition enhances the overall glioma death in response to radiotherapy or chemotherapy (p<0.05) relative to scrambled cells, with a total of 83% versus 50% for irradiation, and 88% versus 67% for TMZ treatment." (PMID 25544764, 2015). "Accordingly, our results show that EPOR silencing on glioma cells increases the toxicity of TMZ and X-rays in GBM cells mainly through the enhancement of senescence leading to the induction of mitotic catastrophe." (PMID 25544764, 2015). "In this study, we determined, in vitro, that EPOR inhibition induces a G2/M arrest of tumour cells, consistent with our previous results showing that EPOR knock-down slows down the glioma growth." (PMID 25544764, 2015). "Silencing EPOR on glioma cells exposed to conventional treatments enhances senescence and induces a robust genomic instability that leads to caspase-dependent mitotic death by increasing the number of polyploid cells and cyclin B1 expression." (PMID 25544764, 2015). "In vitro, we showed that EPOR silencing not only increases the sensitivity of glioma cells to TMZ as well as X-rays but also counteracts the hypoxia-induced chemo- and radioresistance." (PMID 25544764, 2015). "Recently, we and others demonstrated that EPOR signalling on glioma cells, as well as on glioma stem cells, plays an important role in the tumour progression." (PMID 25544764, 2015). "From these results, and according to cell cycle data, EPOR silencing increases apoptosis of glioma cells." (PMID 25544764, 2015). "In contrast, several studies indicated that an in vitro treatment with rHuEPO induces a significant resistance of glioma cells to ionising radiation and drugs which depends on signalling induced by EPOR." (PMID 25544764, 2015). "In this study, we show that EPOR down-regulation, by inducing G2/M cell cycle arrest and senescence of human glioma cells U87 or U251, improves the efficacy of radio- and chemotherapy, in both normoxic and hypoxic conditions." (PMID 25544764, 2015). "Radiobiological parameters estimated from the survival curves also reflect the greater harmful effect of X-rays on glioma cells in which EPOR expression was down-regulated." (PMID 25544764, 2015). "Using RNA interference, we showed on glioma cell lines (U87 and U251) that EPOR silencing induces a G2/M cell cycle arrest, consistent with the slowdown of glioma growth induced by EPOR knock-down." (PMID 25544764, 2015). "The increase in the SER for both U87-shEPOR and U251-shEPOR cells clearly indicates a radiosensitisation potential by inhibiting EPOR on glioma cells." (PMID 25544764, 2015). "It has been recently reported that erythropoietin (EPO) and its receptor (EPOR) are involved in glioma growth." (PMID 25544764, 2015). "HepG2 human hepatoma cells and glioma tissue, known EPOR-positive cells and tissue, were used as positive control." (PMID 22086127, 2012). "Besides these studies with rHuEPO, our work represents the first investigation on the impact of the endogenous EPO/EPOR system present on glioma cells on the efficacy of radio- and chemotherapy." (PMID 25544764, 2015).
glioma (continued). "Collectively, our results suggest that inhibiting EPOR signalling on glioma cells might improve the first-line treatment of GBM." (PMID 25544764, 2015). "Morphological examination of cells also reveals the presence of some large multinucleate cells either after X-rays and TMZ treatments or when glioma cells were depleted in EPOR, indicating that some cells are entering a faulty mitosis without cytokinesis, corresponding to mitotic catastrophe." (PMID 25544764, 2015). "We then sought to determine whether the TMZ chemosensitisation induced by the silencing of EPOR on glioma cells is retrieved in vivo." (PMID 25544764, 2015). "We have shown, at the preclinical level, that EPOR silencing on glioma cells slows down the tumour growth through a proliferative arrest and we now speculate that EPOR signalling could modulate the sensitivity of glioma cells to chemo- or radiotherapy." (PMID 25544764, 2015). "However, compared to the control cells, EPOR down-regulation on U87 or U251 glioma cells increases their sensitivity to radiation in normoxia." (PMID 25544764, 2015). "We then sought to investigate whether the EPOR inhibition on glioma cells could also modulate their chemosensitivity to TMZ." (PMID 25544764, 2015). "Silencing EPOR on glioma cells exposed to ionising radiation (X-rays) or chemotherapy (TMZ) enhances senescence and induces mitotic cell death, an effect that may be through an increase in cyclin B1 expression." (PMID 25544764, 2015). "In basal conditions, we show that the inhibition of EPOR affects the cell cycle of glioma cells with a G2/M arrest accompanied with an increase in the cyclin B1 expression, an indicator of G2/M arrest but not that of cyclin D1 expression, a critical mediator of G1 to S phase progression." (PMID 25544764, 2015). "Since tumour cells in G2/M phase are known to be more radiosensitive, we next determined whether EPOR silencing affected the efficacy of radiotherapy on glioma cells." (PMID 25544764, 2015). "Collectively, these results provide evidence that EPOR is involved in the radiosensitivity of glioma cells not only in normoxia but also in hypoxia conditions." (PMID 25544764, 2015). "Accordingly, we studied the radiosensitivity of glioma cells expressing or not EPOR in response to increasing dose of ionising radiation both in normoxic and hypoxic conditions." (PMID 25544764, 2015). "Recently, the presence of EPOR signaling and EPO-induced cellular proliferation was confirmed in renal cancer cells, head and neck squamous cell carcinomas, and cervical cancer cell lines, as well as glioma cells." (PMID 25426117, 2014). "The OER reaches a value superior to 1 for control and scrambled cells while it decreases to a value of respectively 0.99 and 0.73 for U87-shEPOR and U251-shEPOR cells, confirming the absence of TMZ drug resistance of glioma cells in hypoxic conditions when the EPOR expression is knock-down." (PMID 25544764, 2015). "Indeed, we show that EPOR silencing in glioma cells forces the tumour cells treated with TMZ or ionising radiation toward senescence and mitotic catastrophe, reducing the proliferation capacities of glioma cells and, potentiating and prolonging the effects of the chemo- and radiotherapy." (PMID 25544764, 2015).
hepatocellular carcinoma (7 papers, 2007 to 2023). A malignant tumor that arises from hepatocytes. "As such, increased EPO production and erythrocytosis are demonstrated in patients with hepatocellular carcinoma and relatively increased EPOR expression with decreased EPO level by LPS treatment is possible." (PMID 34831360, 2021). "The Epo/EpoR system is involved in angiogenesis in normal (uterine endometrium) and tumor tissues (human hepatocellular carcinoma)." (PMID 27543111, 2016). "This is in agreement with other authors who showed that the erythropoietin/erythropoietin-receptor system is involved in angiogenesis in human hepatocellular carcinoma." (PMID 27543111, 2016). "So far, the EPO/EpoR system has been indicated as playing a major angiogenetic role in murine models of hepatocarcinogenesis and in vitro studies have indicated the presence of mRNA and protein of both genes in HepG2 and Hep3B hepatoma cell lines." (PMID 23052842, 2013). "Similarly, EPOR and microvessel density significantly correlated with the expression of adrenomedullin, the new metastasis-related and angiogenic regulatory factor involved in tumor angiogenesis, and the recurrence and metastasis of hepatocellular carcinoma and other tumors." (PMID 28703764, 2017). "Microvessel density and mRNA AM and erythropoietin receptor levels were higher in hepatocellular carcinoma than in nontumor tissues." (PMID 36980580, 2023). "In patients with gastric and hepatocellular carcinomas, the levels of EPO/EPOR correlate with angiogenesis and tumor progression; therefore, EPO might serve as an endogenous stimulant of vessel growth by an autocrine and/or paracrine loop." (PMID 28703764, 2017).
acute kidney injury (6 papers, 2009 to 2022). Sudden and sustained deterioration of the kidney function characterized by decreased glomerular filtration rate, increased serum creatinine or oliguria. "Compared with the control group, the expression of EPO and EPOR in the kidney of rats with renal failure was significantly decreased (p < 0.05)." (PMID 31915448, 2019). "Cases with acute renal failure had a lower frequency of EpoR labelling of glia in the brainstem (P = .02)." (PMID 19930602, 2009).
erythroleukemia (6 papers, 2013 to 2025). Acute erythroid leukemia characterised by the presence of at least 50% erythroid precursors and at least 20% myeloblasts in the bone marrow. "Each Db‐Fc was assessed by flow cytometry for binding to TF‐1 cells, which are derived from a human erythroleukemia, display endogenous EPOR, and only grow in the presence of either EPO, granulocyte‐macrophage colony‐stimulating factor (GMCSF), or interleukin 3 (IL‐3)." (PMID 40960423, 2025). "The relation of constitutive EPOR activation with erythroleukemia pathogenesis was introduced early during the 1990s, as the erythroblastosis-inducing spleen focus-forming virus (SFFV) was found to activate EPOR, while activating point mutations of the EPOR also promoted tumorigenesis." (PMID 38892446, 2024). "Amplification of the EpoR gene has been detected in some cell lines derived from AML, CML, and erythroleukemia patients (e.g., UT-7 and TF-1) consistent with their myeloid origin." (PMID 24337485, 2014). "Consistent with this proposal, the erythroleukemia cell line OCIM-1 does not respond to Epo (signaling or proliferation/survival) despite detectable EpoR expression on the cell surface." (PMID 23861852, 2013).
heart failure (6 papers, 2012 to 2024). Inability of the heart to pump blood at an adequate rate to meet tissue metabolic requirements. "For instance, cardiac and skeletal muscle of EpoR-tKO mice are more susceptible to ischemic or toxic injury and also develop more severe heart failure when subjected to pressure overload." (PMID 34142210, 2021). "Taken together with our findings, the EpoR in skeletal muscle could be a novel target to improve skeletal muscle quality in patients with muscle fatigue, mitochondrial myopathies or heart failure-associated exercise intolerance." (PMID 34142210, 2021). "Erythropoiesis-stimulating agents improve the NYHA functional class and decrease the hospital readmission rates for heart failure; however, little is known about the influence of continuous erythropoietin receptor activator (CERA) on the heart." (PMID 36979925, 2023). "Loss of EPOR in the non-erythroid tissue of ΔEPORE mice resulted in decreased ejection fraction and fractional shortening and increased expression of heart failure-associated genes." (PMID 38628440, 2024). "Some previous studies showed that in chronic post-myocardial infarction(MI) heart failure models, EPO increased incorporation of EPCs into the myocardial microvasculature and improved neovascularization, which was associated with increased EPOR and VEGF expression in ischemic hearts." (PMID 22954171, 2012).
lung adenocarcinoma (6 papers, 2008 to 2022). A carcinoma that arises from the lung and is characterized by the presence of malignant glandular epithelial cells. "For example, Xu and Chen utilized a six AG-based pattern (APOC3, EPOR, H2AFX, MXD1, PLCG2, and YWHAZ) to structure a risk model that could efficiently stratify the existing cases in high- and low-risk groups in terms of OS in lung adenocarcinoma (LUAD)." (PMID 34976839, 2021).
multiple myeloma (6 papers, 2016 to 2023). "In order to exclude the possibility of a rhEPO-independent cause for this observation, four additional primary myeloma cell samples were treated with rhEPO in the absence or presence of EPOR blocking antibodies." (PMID 27581518, 2016). "We further asked whether plasma cell expression levels of EPOR was associated with clinical outcomes of myeloma patients." (PMID 27581518, 2016). "Here, we demonstrate that the EPOR is expressed on the cell surface of myeloma cell lines and on primary myeloma cells, and show for the first time active EPO/EPOR signaling in malignant plasma cells." (PMID 27581518, 2016). "Expression of EPOR mRNA in plasma cells from myeloma patients has been shown previously, and it was recently shown that primary myeloma cells expressed EPOR on the surface." (PMID 27581518, 2016). "The relative levels of EPOR mRNA in purified CD138+ cells from 36 myeloma patients and in seven human myeloma cell lines (HMCLs) were quantified with qPCR." (PMID 27581518, 2016). "Together, our results suggest that EPO reduces the viability of primary myeloma cells in an EPOR-dependent manner and that the cells cannot be rescued by stroma cells." (PMID 27581518, 2016). "Increases in phosphorylation of ERK-1/2 and JAK-2 were observed, suggesting that the EPO/EPOR signaling complex is functional in myeloma cells." (PMID 27581518, 2016). "Knockdown of EPOR by short interfering RNA was used to show specific EPOR signaling in the myeloma cell line INA-6." (PMID 27581518, 2016). "Taken together, our results suggest that rhEPO reduces the viability of primary myeloma cells in a specific EPOR-dependent manner that cannot be prevented by stromal cells." (PMID 27581518, 2016). "In isolated primary myeloma cells, the majority (5/6) of samples tested expressed EPOR on their surface with expression ranging from ‘low’ (MM-38) through ‘intermediate’ (MM-40) to ‘high’ expression (MM-39, MM-41 and MM-42)." (PMID 27581518, 2016). "EPO-mediated EPOR signaling reduced the viability of myeloma cell lines and of malignant primary plasma cells in vitro." (PMID 27581518, 2016). "The concomitant observation that higher EPOR expression is associated with survival in four different therapy strategies should encourage further studies to reveal the relevance of EPO/EPOR signaling in multiple myeloma progression." (PMID 27581518, 2016). "Examination of primary myeloma cells for their putative active EPO/EPOR signaling revealed that all samples (MM-51-MM-54) exhibited activation of both ERK-1/2 and JAK-2 after 5 min treatment with 10 U/ml rhEPO." (PMID 27581518, 2016). "Our results encourage further studies to investigate the importance of EPO/EPOR in multiple myeloma progression and treatment." (PMID 27581518, 2016). "We show that the EPOR is expressed in myeloma cell lines and in primary myeloma cells both at the mRNA and protein level." (PMID 27581518, 2016). "We show here that EPO/EPOR signaling is functional in both primary myeloma cells and cell lines and that recombinant human EPO exhibits a negative effect on myeloma cell viability in vitro." (PMID 27581518, 2016). "Four independent survival studies establish a link between elevated EPOR-expression in myeloma cells and beneficial patient outcome and suggest that EPOR expression can be a novel prognostic marker for newly diagnosed myeloma." (PMID 27581518, 2016). "For newly diagnosed myeloma patients in the TT2 (n = 278) and TT3A (n = 245) trials, ROC-high EPOR expression levels were significantly associated with longer overall survival (P = 0.004, hazard ratio = 0.17; P = 0.011, hazard ratio = 0.12, respectively)." (PMID 27581518, 2016). "In order to investigate whether there was an autocrine EPO/EPOR signaling in myeloma cells, we measured expression of EPO mRNA in 20 of the samples." (PMID 27581518, 2016).
multiple myeloma (continued). "Together, this study shows that primary myeloma cells display active EPO/EPOR signaling and that rhEPO may induce myeloma cell death in vitro, both in monoculture and in co-culture of primary cells with myeloma-derived bone marrow stroma cells." (PMID 27581518, 2016). "The role of EPO/EPOR is still unclear in the pathogenesis of multiple myeloma." (PMID 27581518, 2016). "Based on the survival studies, it is therefore intriguing to speculate whether active EPO/EPOR signaling may be favourable for the survival of myeloma patients." (PMID 27581518, 2016). "Cell surface expression of EPOR on six myeloma cell lines was estimated by flow cytometry." (PMID 27581518, 2016). "Interestingly, a recent study has demonstrated that EPO/EPOR could reduce the variability of myeloma cell lines and malignant primary plasma cells." (PMID 38149248, 2023). "Together, these results suggest that EPO/EPOR signaling may operate in myeloma cells." (PMID 27581518, 2016). "Previous investigators also explored how EPO affected the immune status of patients with multiple myeloma and found that the immunomodulatory effects of EPO on lymphocytes, which lack the EPOR, were indirect and occurred by activating macrophages that express EPOR6." (PMID 29391474, 2018). "Hypoxia-dependent erythropoietin (EPO)-receptor (EPOR) signaling is central in various cancers, but the relevance of EPOR signaling in multiple myeloma cells has not yet been thoroughly investigated." (PMID 27581518, 2016). "Activation of EPOR signaling had a negative impact on the viability of myeloma cell lines and of malignant primary plasma cells in vitro." (PMID 27581518, 2016). "Treatment of myeloma cells with EPO was followed by JAK-2 and ERK-1/2 phosphorylation while knockdown of EPOR expression in the myeloma cell line INA-6 reduced JAK-2 and ERK-1/2 phosphorylation, again demonstrating the specificity of active EPO/EPOR signaling in myeloma cells." (PMID 27581518, 2016). "Here, we detected the expression of EpoR in bone marrow-derived endothelial cells from monoclonal gammopathy of undetermined significance (MGUS) and multiple myeloma (MM) patients (MGECs and MMECs, respectively) and assessed whether Epo plays a role in MGECs- and MMECs-mediated angiogenesis." (PMID 26919105, 2016).